TXNIP (thioredoxin interacting protein)
Diseases named in the same sentence as TXNIP in open-access papers (continued):
Sharing a sentence is not in itself a finding about the gene and the disease.
diabetes (continued). "Several studies have documented that TXNIP serves as a key link between cellular stress and inflammatory responses and is also a key pathological regulator of several diseases, including diabetes and neurodegenerative diseases." (PMID 40008893, 2025). "TXNIP knockout mice were protected from renal fibrosis, the accumulation of extracellular matrix, decreases in renal function, and albuminuria after diabetes was induced." (PMID 40076459, 2025). "TXNIP overexpression was induced to examine the reduction in metformin efficacy and to assess the replicability of TXNIP regulation in diabetes animal models." (PMID 40770064, 2025). "Methylation changes in immune-related genes (e.g., TXNIP, ABCG1) have been associated with inflammatory pathways, insulin signaling, and glucose metabolism, thereby contributing to diabetes progression." (PMID 40380284, 2025). "Recent studies have demonstrated that TXNIP release is associated with NLRP3 inflammasome activation and IL-1β production, particularly in contexts of diabetes and oxidative stress." (PMID 39690856, 2025). "As shown in diabetic mouse models, TXNIP deficiency activates antiapoptotic AKT/BCL-xL signaling, increases beta cell mass, and protects against diabetes." (PMID 40559375, 2025). "Diet-induced diabetes by the use of a high-energy diet in sand rats significantly elevates the level of thioredoxin-interacting protein (TXNIP)." (PMID 38540087, 2024). "Thioredoxin-interacting protein (TXNIP) has emerged as a key player in cancer and diabetes since it targets thioredoxin (TRX)-mediated redox regulation and glucose transporter (GLUT)-mediated metabolism." (PMID 38329960, 2024). "It has been recently revealed that thioredoxin-interacting protein (TXNIP), a key element of diabetes progression, activates the NLRP3 inflammasome and subsequent pancreatic B-cell pyroptosis in diabetic mice." (PMID 38248345, 2024). "TXNIP is a multifunctional protein that pathophysiologically regulates cardiovascular diseases and diabetes." (PMID 38789868, 2024). "It was also reported that the inhibition of TXNIP is effective in preventing diabetes complications." (PMID 38248345, 2024). "For instance, verapamil, an anti-hypertensive medication, has been shown to inhibit TXNIP transcription in models of diabetes and Alzheimer’s disease, thus preventing β-cell apoptosis and enhancing glucose homeostasis." (PMID 38790650, 2024). "Previous studies have provided a comprehensive overview of TXNIP’s multiple functions in pathological conditions, highlighting its involvement in diseases such as diabetes, chronic kidney disease, and neurodegenerative disorders." (PMID 39330495, 2024). "While TXNIP is often upregulated in diseases such as diabetes, cardiovascular disorders, and neurodegenerative conditions, it tends to be downregulated in certain types of cancer." (PMID 39330495, 2024). "Significant attention has been given to the role of TXNIP in the context of aging, diabetes or hyperglycemia and age-related comorbidities." (PMID 39075518, 2024). "The ROS-dependent and -independent functions of TXNIP make it an attractive target for drug development in cancer and diabetes treatments, and further research on its molecular mechanism is necessary for the development of a functional and specific drug." (PMID 38329960, 2024). "One of the key regulators of oxidative stress in diabetes is thioredoxin-interacting protein (TXNIP), which acts as an endogenous inhibitor of the antioxidant thioredoxin (TRX)." (PMID 39678047, 2024). "The role of TXNIP as a detrimental factor in islet biology and contributor to the pathogenesis of diabetes has further been demonstrated by multiple groups and by genetic TXNIP deletions." (PMID 39429740, 2024). "Increased TXNIP contributes to inflammatory signalling in endothelial dysfunction in the development of vascular complications of diabetes, insulin resistance and beta-cell dysfunction." (PMID 38199038, 2024).
diabetes (continued). "Over the past two decades, accumulating evidence has strongly established heightened TXNIP activity as a mediator of diabetes pathophysiology." (PMID 39319322, 2023). "TXNIP knockdown mitigated the accumulation of renal tubular lipids in diabetes through the regulation of SCAP, thereby inhibiting the SCAP-SREBP-2 signaling pathway, resulting in reduced cholesterol uptake and synthesis." (PMID 37144033, 2023). "Long-term experiments to observe TXNIP levels and diabetes relapse after bariatric surgery are needed in the future." (PMID 36733403, 2023). "TXNIP inhibition suppressed diabetes induced autophagy and activation of the mTOR signaling pathway." (PMID 37144033, 2023). "EZH2 represses the transcription factor Pax6, which controls expression of the antioxidant inhibitor TXNIP, and in diabetes, downregulation of EZH2 promotes oxidative stress." (PMID 37144033, 2023). "In a previous study of ours, we found that the plasma level of TXNIP was substantially increased in patients with obesity and diabetes." (PMID 36733403, 2023). "A recent high-throughput screen has identified another TXNIP inhibitor SRI-37330, which significantly decreased TXNIP expression, glucagon secretion, and hepatic glucose output, thereby being championed as a potential treatment for diabetes." (PMID 37794178, 2023). "In diabetes, TXNIP has been shown to play a role in the regulation of glucose homeostasis by modulating the activity of pancreatic beta cells, which produce insulin." (PMID 37240157, 2023). "They showed that by reducing β-cell TXNIP expression, verapamil inhibited β-cell apoptosis, enhanced their survival and function, and rescued them from diabetes progression." (PMID 38089047, 2023). "A previous clinical study reported that the serum TXNIP levels were elevated in patients with obesity and diabetes and that bariatric surgery resulted in a significant reduction in serum TXNIP levels as early as 1 month postoperatively." (PMID 36733403, 2023). "TXNIP has already been tested in clinical trials as a therapeutic target for diabetes, suggesting that targeting TXNIP to treat NASH is feasible." (PMID 37153733, 2023). "Uncovering these nutraceutical resources through innovative methods promises new treatment possibilities as emerging evidence continues to position TXNIP as the central molecular linchpin contributing to insulin resistance over progression to overt diabetes." (PMID 39319322, 2023). "Thioredoxin interacting protein (TXNIP) is a potential drug target for type 2 diabetes mellitus (T2DM) treatment." (PMID 36651294, 2023). "TXNIP is a protein sensitive to oxidant conditions whose expression is related to the progression of death in cancer, diabetes, ischemia, and neurodegenerative diseases, among others." (PMID 37547922, 2023). "The importance of methylation in metabolic memory was suggested by the identification of methylation differences, for example in the TXNIP (thioredoxin-interacting protein) locus, in the Diabetes Complications Control Trial (DCCT) cohort." (PMID 36787250, 2023). "In this review, we provide an overview of the multiple functions of TXNIP in pathological conditions and summarize its involvement in various diseases, such as diabetes, chronic kidney disease, and neurodegenerative diseases." (PMID 37394581, 2023). "TXNIP emerged as a viable therapeutic target for diabetes due to its role in pancreatic β-cell apoptosis via activation of the mitochondrial death pathway." (PMID 35456489, 2022). "A number of studies have shown how increased expression of TXNIP makes significant contribution to disease processes, particularly those related to diabetes, but few have related TXNIP to human brain diseases (reviews:)." (PMID 39483368, 2022). "Our findings will be particularly useful for those seeking to better understand the pathophysiological function of TXNIP in order to optimize diabetes medicine." (PMID 35456489, 2022).
diabetes (continued). "TXNIP levels increased significantly in diabetic patients and those with chronic hyperglycemia, suggesting that TXNIP levels are bound up with the development and progression of diabetes." (PMID 35450411, 2022). "Considering the relationship between miR-204 and TXNIP and the relationship of miR-204 with diabetes suggests investigating the effect of miR-204 on the inflammatory pathway in AD." (PMID 36422510, 2022). "The fact that the expression of TXNIP is increased in diabetes and Alzheimer’s disease, and that the expression of TXNIP is decreased in tumor cells also implies a relationship between PDI and TXNIP." (PMID 35314758, 2022). "TXNIP has been studied extensively in relation to diabetes, but few studies have focused on its expression in human AD brains or brains of amyloid plaque-developing AD-model transgenic mice." (PMID 39483368, 2022). "TXNIP acts as a culprit in diseases like diabetes, neurodegenerative diseases, and cerebrovascular diseases." (PMID 35450411, 2022). "TXNIP expression is regulated by a unique E-box motif in the TXNIP promoter, especially in the case of high glucose levels and diabetes." (PMID 36059548, 2022). "This miRNA physiologically downregulates thioredoxin-interacting protein (TXNIP), a physiological inhibitor of thioredoxin antioxidant activity, which is pathologically enhanced in diabetes and cardiovascular disease and involved in inflammation." (PMID 36289710, 2022). "In diabetes pathogenesis, slightly elevated blood sugar levels early in the disease onset enhance TXNIP expression and suppress glucose uptake by cells." (PMID 35164795, 2022). "TXNIP-mediated oxidative stress plays an essential regulatory role in the initiation and development of diabetes, and others." (PMID 35450411, 2022). "The TXNIP/miR-200/Zeb1/E-cadherin signaling pathway links miR-200 to beta cell apoptosis and diabetes and links TXNIP to inhibition of epithelial-mesenchymal transition (EMT), a process involved in beta cell expansion, predicting its decline." (PMID 35903753, 2022). "There was a decreased trend in IRAK-M levels andan increased trend in TXNIP levels with the severity of diabetes." (PMID 36039603, 2022). "Promising results have been obtained in experimental models of diabetes with anti-TXNIP agents, such as S-Equol, SRI-37330, MiR-17-5p, and fluoromethyl ketone (FMK)." (PMID 36017183, 2022). "Researchers found TXNIP is related to cancers, atherosclerosis, diabetes and its complications, neurodegenerative diseases, and cerebrovascular diseases including Alzheimer's disease, stroke, and subarachnoid hemorrhage." (PMID 35450411, 2022). "We found that sitagliptin protected against diabetes-induced oxidative stress by reducing superoxide, TXNIP, PKC, and DNA/RNA/protein oxidative damage, and it prevented the downregulation of NRF2 and antioxidant enzymes, with the exception of catalase." (PMID 35883908, 2022). "Accumulating evidence suggests that TXNIP is upregulated in diabetes and plays a pivotal role in the pathophysiological process of DR." (PMID 36017183, 2022). "Prior studies have suggested the utility of TXNIP as a biomarker for diabetes due to its hyperglycemia-induced overexpression and the strong association of cg19693031 with HbA1c." (PMID 35456489, 2022). "TXNIP appears to be a promising therapeutic target for diabetes, according to growing evidence based on basic, preclinical, and retrospective epidemiological research." (PMID 35722152, 2022). "The inhibition of TXNIP promotes endogenous cell mass and insulin production, thereby becoming an attractive new candidate drug target for diabetes." (PMID 36017183, 2022). "TXNIP is upregulated in β-cells during diabetes and has been shown to induce miR-204 by the inhibition of STAT3 phosphorylation, which in turn directly inhibits MAFA and insulin expression." (PMID 35562869, 2022).
diabetes (continued). "Glucose transporter 1 (or GLUT1), also called the solute carrier family 2, facilitated glucose transporter member 1 (SLC2A1) and thioredoxin-interacting protein (TXNIP) located on chromosome 1 are notable candidate genes for T2D diabetes." (PMID 35164795, 2022). "Diabetes-induced hyperglycemia increased thioredoxin-interacting protein (TXNIP) expression in the kidneys of diabetic mice, resulting in NOX and inflammasome activation, podocyte loss and the onset of albuminuria." (PMID 36618403, 2022). "Minocycline and fenofibrate have demonstrated a protective effect on retinal vascular permeability by reducing ROS-induced TXNIP expression in diabetes." (PMID 36017183, 2022). "Extensive literature is available regarding promising drugs that prevent retinal microvascular dysfunction induced by diabetes, directed at TXNIP." (PMID 36017183, 2022). "Thioredoxin-interacting protein (TXNIP) is one of the genes which is strongly induced early in diabetes and by high glucose in all tissues examined so far, including retinal and renal cells." (PMID 34940029, 2021). "For example, there is a correlation between TXNIP and peripheral nerve conduction velocity in patients with diabetes." (PMID 33567593, 2021). "Thioredoxin-interacting protein (TXNIP), an endogenous inhibitor of thioredoxin, is documented to regulate diabetes-accelerated AS." (PMID 33638792, 2021). "The role of TXNIP, using paw-level anti-TXNIP siRNA injections in a mouse model of lower limb ischemia and diabetes, provides some insight." (PMID 33567593, 2021). "Several preclinical and clinical evidence related to diabetes mellitus supported the TXNIP-specific inhibitors for the development of new promising agents, such as Verapamil, Taurine, and SRI-37330." (PMID 34335280, 2021). "Recently research demonstrated that TXNIP played important role in glucose metabolism, and high glucose condition up-regulated the expression of TXNIP, respectively, in cells and diabetes rats." (PMID 34881312, 2021). "TXNIP is defined as a pro-oxidative stress, pro-inflammatory, and pro-apoptotic protein induced in diabetes and its complications." (PMID 34940029, 2021). "Data from the literature identify TXNIP as a potential target in diabetes complications such as diabetic retinopathy, nephropathy, cardiomyopathy, and impaired post-ischemic revascularization." (PMID 33567593, 2021). "TXNIP has been reported to be elevated in the multiple tissues in diabetes mellitus and has detrimental effects on cell function and metabolism." (PMID 34162834, 2021). "TXNIP has been implicated as the link between chronic hyperglycaemia and β cell death, and elevated TXNIP mRNA has been found in islets isolated from subjects with diabetes." (PMID 34948127, 2021). "TXNIP is an oxidative stress-sensitive activator in cellular redox balance and is involved in the progression of diabetes, and we found that high glucose increased expression of TXNIP in a glucose dose-dependent manner." (PMID 34881312, 2021). "Increased expression of TXNIP functions as a major role in β cell failure and dysfunction during diabetes development." (PMID 34881312, 2021). "The inhibition of the TXNIP expression through the activation of the AMPK pathway induces protective effects against diabetes following treatment with bakuchiol or sulforaphane, which induces the Trx protein." (PMID 34401074, 2021). "The thioredoxin-interacting protein (TXNIP) gene plays an important role in redox regulation and is a marker gene for diabetes that responds to glucose metabolism and inflammation." (PMID 34433867, 2021). "We show that diabetes induces TXNIP expression, redox stress, and Müller glia activation (gliosis) in rat retinas when compared to non-diabetic rat retinas." (PMID 34940029, 2021). "TXNIP has been reported to play a vital part in diabetes during the immune response by activating the inflammatory pathway via the NLRP3 (NOD-, LRR-, and pyrin domain–containing protein 3) inflammasome." (PMID 33803178, 2021).
diabetes (continued). "The potential for therapeutic advantages of targeting TXNIP in diabetes and the future direction of the study are also discussed." (PMID 32824669, 2020). "The stress-induced upregulation of TXNIP is observed in the pancreatic islets during the progression of diabetes in both mice and humans." (PMID 32824669, 2020). "In this review, we summarize the decades of work analyzing TXNIP as a master regulator of glucose homeostasis by integrating its function, physiological role, and diabetes development." (PMID 32824669, 2020). "TXNIP has been identified in disease mechanisms involved in various cancers, diabetes mellitus, cardiovascular disease, renal disease, and retinal disease, among others." (PMID 33302545, 2020). "Tissue specific physiological role of TXNIP give us a lesson to learn the targeting tissues for each specific condition in diabetes." (PMID 32824669, 2020). "The involvement of TXNIP in diabetes, pancreatic beta-cell death, and glucose metabolism has been the focus of several recent review articles." (PMID 33302545, 2020). "After adjusting for age, course of diabetes, FBG, HblAc, vitamin D3, SDBG, and MBG, TXNIP was still an independent risk factor for NCV abnormality (OR = 2.001, P = 0.047)." (PMID 32774321, 2020). "TXNIP is important because of its wide range of functions in cardiovascular diseases, neurodegenerative diseases, cancer, diabetes, and other diseases." (PMID 33194655, 2020). "Thioredoxin-interacting protein, TXNIP, expression is strongly induced by diabetes and high glucose (HG) levels in all tissues examined, including different cell types in the retina." (PMID 31023645, 2019). "One of the genes strongly induced by diabetes and aging in retinal cells and neurons is the thioredoxin-interacting/inhibiting protein (TXNIP)." (PMID 31649499, 2019). "Tissue-specific Foxo1 overexpression in transgenic mice had a protective effect on the renal function and partially reversed tubular injuries by attenuating the diabetes-induced increase in TXNIP and decrease in the TRX levels." (PMID 30962862, 2019). "Additional studies will be required to identify TxNIP O-GlcNAcylation sites, and to establish the specific contribution of TxNIP O-GlcNAcylation to pancreatic glucotoxicity in diabetes." (PMID 31164864, 2019). "In support, inhibition or deletion of TXNIP in mouse β-cells protects against β-cell apoptosis and diabetes." (PMID 31623194, 2019). "In the current study, two rodent models of diabetes (GK rats and db/db mice) suggested O-GlcNAcylation of TxNIP in pancreatic cells." (PMID 31164864, 2019). "TXNIP (Thioredoxin-interacting protein) is a key mediator of diabetic β-cell apoptosis and dysfunction in diabetes, and thus, its regulation represents a therapeutic target." (PMID 31505737, 2019). "Increased TRX1 and decreased TXNIP are beneficial for preventing hyperinflammation, neurodegeneration, and the progression of diabetes." (PMID 30189890, 2018). "Thioredoxin-Interacting Protein, TXNIP, is strongly induced by diabetes and high glucose in all tissues examined including the pancreatic beta cells and the retina." (PMID 31355358, 2018). "We and others have shown that a protein called thioredoxin-interacting protein (TXNIP), both protein and mRNA, is strongly induced by diabetes and high glucose in all tissues examined including pancreatic beta, renal and retinal cells." (PMID 31355358, 2018). "In the Akita model, deletion of TXNIP protected against β-cell apoptosis and ameliorates diabetes severity." (PMID 29556237, 2018). "Increased expression of TXNIP and reduced Trx activity have been observed in animal models of diabetes." (PMID 30298051, 2018). "In a rat model of diabetes, increased intracellular ROS upregulated the thioredoxin-interacting protein (TXNIP), which facilitates activation of the NLRP3 inflammasome." (PMID 30210334, 2018).